RNU6-674P (RNA, U6 small nuclear 674, pseudogene)
Gene: Small nuclear RNA gene on chromosome 2 (85,204,926 to 85,205,032, forward strand). Ensembl gene ENSG00000200701.
Homologues: Orthologues: macaque U6 (93% identical), guinea pig U6 (75% identical), mouse Gm25205 (75% identical), rat LOC120102600 (74% identical). Paralogues in human: RNU6-333P (85% identical), RNU6-12P (84% identical), RNU6-13P (84% identical), RNU6-16P (84% identical), RNU6-32P (84% identical), RNU6-460P (84% identical), RNU6-61P (84% identical), RNU6-820P (84% identical), RNU6-1 (83% identical), RNU6-1005P (83% identical), RNU6-1020P (83% identical), RNU6-11P (83% identical), and 1290 more.